MTAP (methylthioadenosine phosphorylase)
Diseases named in the same sentence as MTAP in open-access papers (continued):
Sharing a sentence is not in itself a finding about the gene and the disease.
cancer (continued). "Loss of S-methyl-5′-thioadenosine phosphorylase (MTAP) expression offers a therapeutic option through synthetic lethality and confers resistance to immune checkpoint inhibitors in various cancers." (PMID 40554389, 2025). "Given this synthetic lethal interaction, MAT2A has emerged as a promising therapeutic target, with several inhibitors currently in clinical development for the treatment of MTAP-deleted cancers." (PMID 40430308, 2025). "One of the most common genetic abnormalities in patients with various types of cancer (including glial tumors of the CNS) is the deletion of the MTAP gene." (PMID 41465382, 2025). "MTAP biallelic deletion stands out as one of the most prevalent oncogenic events across a diverse range of cancers." (PMID 40590219, 2025). "In a phase I expansion study, IDE397 showed good dose-dependent tolerability in cancer patients with MTAP deletion." (PMID 41465382, 2025). "The last genetic biomarkers of our review are the 5-methylthioadenosine phosphorylase (MTAP) deletions which are present in 10–15% of all cancers, co-occurring in 80–90% of CDKN2A-deleted malignancies." (PMID 41153346, 2025). "The versatility of MTAP in exposing vulnerabilities in cancer cells warrants a fresh perspective to reevaluate multiple therapies investigated over the years." (PMID 41439984, 2025). "The discovery of MTA-uncompetitive PRMT5 inhibitors has galvanized drug discovery efforts to generate precision cancer medicines since MTA is elevated in many cancers due to deletion of MTAP, thereby exposing a synthetic lethal vulnerability." (PMID 41339334, 2025). "On the other hand, MRTX1719 selectively targets the PRMT5/metabolite methylthioadenosine (MTA) complex, which is elevated in cancers with the deletion of methylthioadenosine phosphorylase (MTAP)." (PMID 40723820, 2025). "MAT2A inhibitors were developed later than PRMT5 inhibitors and only two molecules are in Phase II clinical trials concerning cancer patients with MTAP deletion." (PMID 41465382, 2025). "MRTX1719 was characterized as a substrate-competitive, MTA-cooperative inhibitor with selectivity for MTAP-deleted cancer cells." (PMID 41339334, 2025). "The diverse role of MTAP appears to be context-dependent, varying across cancer types and cellular environments, which underscores the need to design interventions that are unique to each tumor type." (PMID 41439984, 2025). "MTAP loss leads to MTA accumulation, making MTAP-deficient cancer cells susceptible to PRMT5 inhibition." (PMID 40362535, 2025). "It is an oral, reversible, highly potent and selective MAT2A inhibitor that has been shown to be active against MTAP-deleted cancer cells in cell cultures and animal models." (PMID 41465382, 2025). "BMS-986504 (MTRX1719) is the second generation of MTA-cooperative PRMT5 inhibitors designed to preferentially bind to the PRMT5-MTA complex which accumulates in cancer cells with MTAP deletion." (PMID 41465382, 2025). "MTAP staining was significantly stronger in cancers harboring the TMPRSS2:ERG fusion than in ERG fusion negative tumors (p < 0.0001)." (PMID 40554389, 2025). "These would selectively inhibit thegrowth of MTAP-del cancer cells in contrast to MTAP-wild type cells(MTAP-WT) increasing the safety margin." (PMID 40102181, 2025). "AM-9934 inhibits PRMT5 only in the presence of MTA and selectively impairs proliferation of MTAP -deleted cancer cells and growth of MTAP−/− tumors while sparing MTAP+/+ cells." (PMID 40377999, 2025). "The MAT2A inhibitor, such as IDE397, selectively induces synthetic lethality in MTAP-deficient malignancies, while SLC7A5 inhibitors, such as JPH203, exert anti-cancer activity by blocking SLC7A5." (PMID 40430461, 2025). "MTAP is frequently deleted in various cancers, including TNBC, often as a codeletion event with cyclin-dependent kinase inhibitor 2A (CDKN2A)." (PMID 40590221, 2025).
cancer (continued). "It has been demonstrated that MTAP deficiency, leading to MTA accumulation, offers a therapeutic window by creating a hypomorphic PRMT5 state that selectively sensitizes cancer cells to PRMT5 inhibition." (PMID 40603833, 2025). "During optimization,robust cell-based activity was achieved, creating a near-completereduction (>80%) in symmetric dimethyl arginine (SDMA) leadingtodecreased cell viability of MTAP-del HCT116 cancer cells." (PMID 40102181, 2025). "Given that MTAP deletion occurs in approximately 15% of human cancers, identifying novel, well-tolerated therapies that target both metabolic vulnerabilities and immunosuppressive features is a critical unmet need." (PMID 41246302, 2025). "In this study, we demonstrated that MTAP plays a dual role in cancer by regulating both tumor progression and immune responses." (PMID 41246302, 2025). "Fluorescence in situ hybridization analysis of 9 MTAP-negative cancers confirmed homozygous MTAP deletion in all of these tumors." (PMID 40554389, 2025). "A clinical phase 1 trial has shown significant size reduction of MTAP‐deleted cancers after treatment with the PRMT5 inhibitor MRTX1719." (PMID 39668577, 2025). "In another example, the MTA-cooperative PRMT5 inhibitor, MRTX1719, demonstrates significant inhibitory effects on cancer cells with MTAP deletions by selectively binding to the PRMT5/MTA complex." (PMID 39826691, 2025). "Another PRMT5 inhibitor of MRTX1719 exhibits synthetic lethality in preclinical models and activity in phase I trial for patients with MTAP-null cancer, The efficacy remains to be investigated in late-stage trials." (PMID 40590219, 2025). "PRMT5 has been identified as a synthetic lethal target in cancers with a homozygous deletion of the MTAP gene, which is commonly co-deleted with the tumor suppressor gene CDKN2A." (PMID 40362535, 2025). "This preclinical and early clinical data support a synthetic lethal strategy targeting PRMT5 in MTAP-deleted cancers." (PMID 39885614, 2025). "GSK3368715 (also known as EPZ019997) is a selective PRMT1 inhibitor that demonstrated enhanced antitumor activity in MTAP-deleted cancer cells." (PMID 41204384, 2025). "Loss of MTAP leads to accumulation of MTA, which competitively binds to the active domain of the PRMT5 enzyme, thereby increasing cancer cell dependence on PRMT5." (PMID 41439984, 2025). "The enzyme S-methyl-5′-thioadenosine phosphorylase (MTAP) is of topical interest because its inactivation by homozygous deletion occurs commonly in cancer and offers several new therapeutic options." (PMID 40554389, 2025). "In summary, a rationallydesigned mechanism switch was achievedin a series of compounds that selectively inhibit the PRMT5•MTAcomplex relative to the PRMT5•SAM complex and selectively kill MTAP-deleted cancer cells relative to MTAP WT cells." (PMID 39919252, 2025). "Loss of MTAP leads to reduced salvage of methionine and adenine from MTA in cancer cells, resulting in increased dependency on an exogenous supply of these nutrients." (PMID 41439984, 2025). "Loss of the metabolic enzyme 5′-methylthioadenosine phosphorylase (MTAP, EC:2.4.2.28) is the most frequent metabolic gene deletion in human cancers due to its close (100 kb) sequence proximity to the CDKN2A/B locus." (PMID 38000655, 2024). "What's more, MTAP loss results in the accumulation of methylthioadenosine (MTA), which inhibits protein arginine methyltransferase 5 (PRMT5) activity and leads to reduced basal PRMT5 methylation in MTAP‐deleted cancers." (PMID 39711357, 2024). "It was reported that IDE397 exhibited inhibition of MAT2A activity with IC50 of about 10 nM and antiproliferation effect on MTAP−/− cancer cells with IC50 of about 20 nM." (PMID 39309689, 2024). "In MTAP−/− cancer cell lines, MAT2a inhibitor AG-270 has a reported IC50 of 260 nM for growth inhibition." (PMID 38000655, 2024).
cancer (continued). "The selective antiproliferation of MTAP−/− cells indicated a viable therapeutic approach to MTAP naturally deleted cancer cells." (PMID 39309689, 2024). "The reduction of SAM, along with the accumulation of MTA, contributes to reducing PRMT5 activity and leads to antiproliferative effects in MTAP‐deleted cancer cells and tumors." (PMID 39309689, 2024). "On the contrary, frequent deletion of the methylthioadenosine phosphorylase gene was reported in many tumor-derived cell lines and types of cancer, including breast." (PMID 39063133, 2024). "As such, cancers harboring MTAP deletion are more sensitive to additional PRMT5 inhibition than normal cells." (PMID 39337530, 2024). "Through inhibition of MAT2A or PRMT5, exploiting the synthetic lethality cascade, novel therapeutic modalities have emerged, holding promise for cancers presenting MTAP deletion, including metastatic pancreatic malignancies." (PMID 39001391, 2024). "Loss of MTAP leads to the accumulation of MTA and renders these cancer cells vulnerable to inhibition of protein arginine methyltransferase 5 (PRMT5)." (PMID 38698089, 2024). "It has been shownthat PRMT5 inhibition by small molecules canselectively kill cancer cells with homozygous deletion of the MTAP gene if the inhibitors can leverage the consequenceof MTAP deletion, namely, accumulation of the MTAPsubstrate MTA." (PMID 38595098, 2024). "Therapies targeting of MAT2A, RIOK1, or other PRMT5 co‐complex members selectively affect MTAP‐deleted cancers while sparing MTAP‐expressing normal tissues, which address the unmet clinical need of human cancers with the deletion of the MTAP locus." (PMID 39711357, 2024). "Previous reports demonstrate that MTAP inhibition alone has growth-inhibitory effects in select cell lines in culture, xenografts and cancer genetic models, modulated through the intracellular accumulation of MTA." (PMID 38000655, 2024). "This work investigates the potential of MTDIA to induce the MTAP−/− synthetic lethal phenotype in MTAP+/+ cancers when combined with MAT2a inhibitors." (PMID 38000655, 2024). "Despite the cellular adaptation, SCR‐7952 exhibited promising antiproliferative activity on MTAP‐deleted cancer cells, more potent and selective than AG‐270, which was presumably a result of its high enzyme activity." (PMID 39309689, 2024). "Considering the 8.7‐fold difference of the antiproliferative effect of SCR‐7952 and AG‐270 on HCT116 MTAP−/− cancer cells (34.4 vs. 300.4 nM), the significantly lower therapeutic dosage of SCR‐7952 was reasonable." (PMID 39309689, 2024). "Here, we described a novel MAT2A inhibitor, SCR‐7952 with potent and selective antitumor effects on MTAP‐deleted cancers in both in vitro and in vivo." (PMID 39309689, 2024). "MTA competed with SAM for binding to PRMT5 as an endogenous inhibitor, and the reduction of SAM was deduced to sensitize the effect of MTA‐cooperative inhibitors in MTAP‐deleted cancer cells." (PMID 39309689, 2024). "Homozygous 5′-methylthioadenosine phosphorylase (MTAP) deletions occur in approximately 15% of human cancers." (PMID 38000655, 2024). "The metabolic enzyme methionine adenosyltransferase 2A (MAT2A) was found to elicit synthetic lethality in methylthioadenosine phosphorylase (MTAP)‐deleted cancers, which occur in about 15% of all cancers." (PMID 39309689, 2024). "SCR‐7952 selectively inhibited the growth of MTAP‐deleted cancers, via the regulation of PRMT5 activity." (PMID 39309689, 2024). "We discovered a potent and specific allosteric MAT2A inhibitor SCR‐7952, with promising inhibition on the growth of MTAP‐deleted cancers, via the regulation of PRMT5 activity and its downstream." (PMID 39309689, 2024). "The drug synergy afforded by combination MTDIA and AG-270 treatment suggests that MTDIA has the potential to expand the use of MAT2a inhibitors to CRCs and other cancers that are MTAP+/+." (PMID 38000655, 2024).
cancer (continued). "SCR‐7952 selectively suppressed MTAP‐deleted cancer cell proliferation in vitro and tumor growth in vivo, via regulation of PRMT5 activity and its downstream splicing perturbations." (PMID 39309689, 2024). "Therapeutic strategies that are proven effective in MTAP‐deleted cancers such as PRMT5 inhibitors and MTA‐cooperative PRMT5 inhibitors should be investigated in the context of low MTA AML." (PMID 39259513, 2024). "The interaction between MTAP loss and codeletions in MAT2a or PRMT5 is characterized as synthetic lethal in cancers." (PMID 38000655, 2024). "The contribution of the MTAP-ANRIL fusion is also critical when assessing the involvement of ANRIL in cancer biology." (PMID 37627188, 2023). "Homozygous deletion of the methylthioadenosine phosphorylase (MTAP) is frequently found in some types of cancer, and the application of purine analogue has been shown to be effective therapeutic option in MTAP deletion cancer patients." (PMID 36968583, 2023). "In cancer cells, the MTAP gene is frequently co-deleted with CDKN2A, and this results in MTA-mediated inhibition of the methyltransferase PRMT5; in line with this, the sensitivity to PRMT5 inhibitors is higher in cells with increased MTA levels." (PMID 37563469, 2023). "Truncated MTAP proteins resulting from point mutations in the last three exons of MTAP can physically interact with the wild-type MTAP protein, a tumor suppressor in several human cancers." (PMID 37277447, 2023). "Homologous deletions of MTAP are found in 40% of GB cases, resulting in a dependence of cancer cells on Protein Arginine Methyltransferase 5 (PRMT5)." (PMID 37298093, 2023). "AMG 193 has shown potential inhibition in a patient-derived xenograft model as well as MTAP-null cancer cell lines." (PMID 38136401, 2023). "Targeting SAM or MAT2A has proven beneficial among several type of cancers, especially in MTAP-deleted cancers." (PMID 36891236, 2023). "Because they are more sensitive to PRMT inhibition, MTAP-deleted cancers can be selectively targeted." (PMID 38134182, 2023). "The 9p21.3 region, which contains the three tumor suppressor genes CDKN2A, CDKN2B and MTAP, is known to be frequently deleted in different types of cancer cells." (PMID 36762651, 2023). "Studies show that methionine adenosyltransferase 2A (MAT2A) inhibitors induce synthetic lethality of MTAP-deleted cancer, especially in combination with taxanes and gemcitabine, which demonstrate a potential to treat MPM of the nuclear DAMPs subtype." (PMID 37033966, 2023). "The MTAP gene, which is located at the chromosomal locus 9p21, is deleted in many human cancers because of its proximity to the tumor suppressor gene cyclin-dependent kinase inhibitor 2A." (PMID 36831453, 2023). "PRMT5 ablation alone also recapitulates FA pathway deficiency seen in MTAP-deleted tumors, mimicked by the use of MAT2A inhibitors in MTAP-deleted cancers that was found to be synergistic with docetaxel in squamous lung and pancreatic PDX models." (PMID 37861290, 2023). "For MTAP−/− cancer cells, class 2 inhibitors working in synergy with MTA are desired to suppress or kill them more specifically while sparing MTAP+ cells." (PMID 36192627, 2022). "Search for MTA-synergic PMRT5 inhibitors that work more potently in MTAP−/− cancer cells asks for a different strategy." (PMID 36192627, 2022). "Although MTAP deletion sensitizes cancer cells to PRMT5 depletion, pharmacologic inhibition of PRMT5 by a specific small‐molecule inhibitor shows only modest selective tumor cytotoxicity." (PMID 35766227, 2022). "Next, we analyzed the correlation between MIR31HG expression and the deletion of these three genes (CDKN2A, CDKN2B, and MTAP) in 807 cancer cell lines from the CCLE database." (PMID 35570408, 2022). "The deficiency of MTAP results in impaired PRMT5 activity and thus sensitizes cancer cells to GSK3368715." (PMID 36572880, 2022).
cancer (continued). "More recent studies have identified MAT2A as a viable target in MTAP-deleted cancers, and clinical development has begun for the MAT2A inhibitor, AG-270." (PMID 35804819, 2022). "For example, co-deletion of genes near p16 including MTAP and several interferons is common in several cancers, and subsequently all these drivers paired with MAT2A as the SL partner." (PMID 36517508, 2022). "MTAP loss in GBM has its impact on multiple aspects—co-deletion of CDKN2A, prognosis, metabolism pathway, immunosuppressive profile, and cancer cell stemness among others." (PMID 36572880, 2022). "~15% of all human cancers lack MTAP (MTAP-) and accumulate by 5–20 folds a metabolic derivative—5′-methylthioadenosine (MTA)—of S-adenosyl-l-methionine (SAM), the cofactor for PRMT5 catalytic activity." (PMID 36192627, 2022). "In sum, these data suggest PRMT5‐mediated sDMA modification negatively regulates the stability of vimentin, and the stabilized vimentin compels the invasion of MTAP‐deleted cancer." (PMID 35766227, 2022). "The high frequency of MTAP deletion in tumors, along with its ubiquitous expression in normal tissues, has made the MTAP-pathway alteration a potential target of interest for cancer therapy." (PMID 35963436, 2022). "Deletion of MTAP results in increased dependency on PRMT5 in cancer cells thus providing the potential avenues for targeted therapies." (PMID 36572880, 2022). "IDE397 is a differentiated small molecule inhibitor with great potential for MTAP-deleted cancer patients." (PMID 36572880, 2022). "AG-270 is a safe, tolerable and first-in-class oral MAT2A inhibitor that reduces the proliferation of cancer cells and tumors that lack MTAP." (PMID 36572880, 2022). "Methylthioadenosine phosphorylase (MTAP), a recently identified tumor suppressor, was shown to render cancer cells sensitive to methionine restriction by lowering SAM levels." (PMID 35600583, 2022). "Although a high percentage of MTAP deletion was found in several clinicopathologic cancer studies, MTAP gene deletion associated with the invasive and/or metastatic processes is the first time to be mentioned." (PMID 35766227, 2022). "We noticed that the invasion‐suppressive ability of enzyme‐defective D220A mutant MTAP which fails to catalyze MTA was attenuated, suggesting that the enzymatic activity of MTAP is critical for its cancer suppressive function." (PMID 35766227, 2022). "The growth of MTAP-deleted cancer cells is blocked as a result of MAT2A inhibition which lowers PRMT5-dependent mRNA splicing and prompts DNA damage." (PMID 36572880, 2022). "Second, some cancers lack methylthioadenosine phosphorylase (MTAP), an enzyme allowing the synthesis of methionine from methylthioadenosine by the polyamine pathway, either because the MTAP gene is methylated or co-deleted with the tumor suppressor gene p16." (PMID 35631199, 2022). "An important anti-cancer application for MTDIA, beyond that implied by the APCMin/+ model, is the pharmacological induction of the MTAP−/− physiological state in cancers that are genetically MTAP+/+." (PMID 33893330, 2021). "The chromosome 9p21 (chr9p21) locus, which encodes the CDKN2A gene, is homozygously deleted in approximately 15% of all human cancers, with frequent codeletion of the MTAP gene, in 80–90% of tumors, along with CDKN2A deletion." (PMID 34006904, 2021). "In the literature, we noticed large discrepancies between different studies in the magnitudes of reported MTA increases in MTAP-deleted versus MTAP-intact cancer cell lines." (PMID 34244484, 2021). "The significant investigation into the design of PRMT5 and MAT2A inhibitors in recent years makes the possibility of co-inhibition of MTAP a new possibility for MTAP+/+cancers as well as its use as a monotherapy." (PMID 33893330, 2021). "Current efforts toward MAT2A inhibitor development are focused towards treating MTAP−/− cancers, with agent AG-270 in clinical trials enrolling patients with MTAP-deleted solid tumors (NCT03435250)." (PMID 33893330, 2021).